KLHL2P1 (kelch like family member 2 pseudogene 1)
Synonyms: MAVP1
Gene: Transcribed unprocessed pseudogene on chromosome 4 (119,334,329 to 119,378,233, forward strand). Ensembl gene ENSG00000250412.
Diseases named in the same sentence as KLHL2P1 in open-access papers:
KLHL2P1 is named in the same sentence as 2 diseases in open-access papers, as found by Europe PMC text mining. Sharing a sentence is not in itself a finding about the gene and the disease. The quoted sentences say what the papers report.
HIV-1 infection (1 paper, 2015). The type species of lentivirus and the etiologic agent of acquired immunodeficiency syndrome (AIDS). "Several functional genes similar to pseudogene KLHL2P1 are downregulated in HIV-1 infection." (PMID 26426037, 2015).
viral infection (1 paper, 2015). "In contrast, FOXK1 (parent gene of KLHL2P1) is downregulated only in early viral infection (a >1.5-fold decrease in expression and downregulation in all nine datasets at 12 h and six datasets at the 24-h time point)." (PMID 26426037, 2015).